SULT1A4 (sulfotransferase family 1A member 4)
Description:
Sulfotransferase that utilizes 3'-phospho-5'-adenylyl sulfate (PAPS) as sulfonate donor to catalyze the sulfate conjugation of phenolic monoamines (neurotransmitters such as dopamine, (R)- adrenaline/epinephrine, (R)-noradrenaline/norepinephrine and serotonin) and phenolic and catechol drugs. Catalyzes the sulfation of T4 (L-thyroxine/3,5,3',5'-tetraiodothyronine), T3 (3,5,3'-triiodothyronine), rT3 (3,3',5'-triiodothyronine) and 3,3'-T2 (3,3'-diiodothyronine), with a substrate preference of 3,3'-T2 > rT3 > T3 > T4.
Synonyms: ST1A4; HAST3; M-PST; ST1A3; ST1A3/ST1A4; STM; TL-PST
Tractability: Small molecule: a structure with a bound ligand is known. PROTAC: ubiquitination databases record sites on it.
Gene: Protein-coding gene on chromosome 16 (29,458,993 to 29,464,966, forward strand). Ensembl gene ENSG00000213648.
Subcellular location: Cytoplasm
Pathways (Reactome):
Drug ADME: Paracetamol ADME
Metabolism: Cytosolic sulfonation of small molecules
Gene Ontology:
Molecular function: protein binding; sulfotransferase activity; aryl sulfotransferase activity
Biological process: dopamine metabolic process; epinephrine metabolic process; norepinephrine metabolic process; serotonin metabolic process; sulfation; thyroid hormone metabolic process; sulfur compound metabolic process
Cellular component: cytoplasm; cytosol
Homologues: Orthologues: chimpanzee SULT1A3 (98% identical), macaque SULT1A3 (64% identical), tropical clawed frog sult1b1 (50% identical), zebrafish sult1st2 (49% identical), zebrafish sult1st3 (49% identical), zebrafish sult1st7 (49% identical), zebrafish sult1st9 (49% identical), zebrafish sult1st1 (48% identical), zebrafish sult1st4 (47% identical), tropical clawed frog sult5a1 (40% identical), zebrafish sult5a1 (40% identical), zebrafish sult2st3 (39% identical), and 8 more. Paralogues in human: SULT1A3 (100% identical), SULT1A1 (93% identical), SULT1A2 (90% identical), SULT1C4 (54% identical), SULT1B1 (53% identical), SULT1C2 (51% identical), SULT1C3 (49% identical), SULT1E1 (48% identical), SULT2B1 (37% identical), SULT2A1 (36% identical), SULT4A1 (35% identical), SULT6B1 (31% identical).
Diseases named in the same sentence as SULT1A4 in open-access papers:
SULT1A4 is named in the same sentence as 2 diseases in open-access papers, as found by Europe PMC text mining. Sharing a sentence is not in itself a finding about the gene and the disease. The quoted sentences say what the papers report.
Parkinson’s (1 paper, 2024). "It is noteworthy that SULT1A4 shares an important paralogous relationship with SULT1A3, and several studies have posited a potential association between the copy number of SULT1A3/4 and neurodegenerative diseases such as Parkinson’s and Alzheimer’s." (PMID 39329723, 2024).
SULT1A4 also shares sentences with these, for which no sentence is quoted: neurodegenerative disease (1 paper).